XPO1 (exportin 1)
Diseases named in the same sentence as XPO1 in open-access papers (continued):
Sharing a sentence is not in itself a finding about the gene and the disease.
cancer (continued). "Nuclear export factor chromosomal region maintenance 1 (CRM1; Xpo1 and exportin-1) controls cellular localization and function of numerous proteins that are critical for the development of many cancer hallmarks." (PMID 29263896, 2016). "From this perspective, inhibition of the XPO1-mediated nuclear export by selective inhibitor of nuclear export (SINE) compounds has shown broad-spectrum anti-cancer activity." (PMID 27634897, 2016). "We predicted that sensitive cells would have increased XPO1 occupancy at a lower drug concentration, and therefore utilize a patient's cancer cells to predict a positive response to selinexor." (PMID 26654943, 2016). "In cancer, over expression of XPO1 protein results in an aberrant distribution of TSPs to the cytoplasm where they are rendered ineffective at surveying genomic damage and preventing abnormal cell growth." (PMID 26654943, 2016). "When we integrate these complementary and orthogonal methods, we identify and evaluate CDK4 and XPO1 as potential therapeutic targets in this cancer." (PMID 27329820, 2016). "These homozygous genome-edited XPO1C528S Jurkat cells were viable and showed a >250 fold resistance to SINE compounds, demonstrating that the anti-cancer activity of SINE compounds effectively results from XPO1 inhibition." (PMID 27634897, 2016). "Inhibition of XPO1 is one approach to restore nuclear localization and activation of multiple TSPs, allowing them to function properly and induce cancer-specific apoptosis." (PMID 27693556, 2016). "These cargo proteins include tumor suppressors and growth-regulatory factors and as such XPO1 is considered a potential anti-cancer target." (PMID 27634897, 2016). "XPO1 inhibition locks cargo proteins, including TSPs, in the nucleus leading to selective apoptosis of cancer cells, whereas, normal cells undergo transient cell cycle arrest." (PMID 27713151, 2016). "Exportin 1 (XPO1) is a well-characterized nuclear export protein whose expression is up-regulated in many types of cancers and functions to transport key tumor suppressor proteins (TSPs) from the nucleus." (PMID 26573568, 2015). "Our results show that SINE compounds, which inhibit XPO1 activity, have anticancer effects in in vitro and in vivo models of human cancer." (PMID 26620414, 2015). "For these reasons, we focused our attention of XPO-1 inhibition as therapeutic tool for the treatment of cancer, including PCa." (PMID 26620414, 2015). "Anti-cancer/anti-fungal XPO1 inhibitors have been isolated from myxobacterium Sorangium cellulosum in a soil sample collected in Cala Ratjada (Mallorca, Spain) by Höfle, Reichenbach and others in 1995." (PMID 25476752, 2014). "Of all the potential targets in nuclear cytoplasmic transport, the nuclear export receptor XPO1 remains the best understood and most advanced therapeutic target for the treatment of cancer." (PMID 25476752, 2014). "Several studies have now demonstrated that adequate function of XPO1 is necessary for cancer cells to survive." (PMID 24503695, 2014). "In culture, normal cells tolerate prolonged XPO1 blockade (up to 4−5 days), whereas cancer cells will initiate an apoptotic program after 8−12 hours of exposure to SINE compounds." (PMID 25057921, 2014). "Because of this, nuclear export inhibition through XPO1 is a potential target for therapeutic intervention in many cancers." (PMID 25476752, 2014). "In summary, this phase I clinical trial represents the first evaluation of a novel oral XPO1 inhibitor in a spontaneous large animal model of cancer." (PMID 24503695, 2014). "Given the role of XPO1 dysregulation in cancer, there has been great interest in developing inhibitors of this protein." (PMID 25022346, 2014). "An orally-active synthetic small molecule, CBS9106, which reversibly blocks XPO1-mediated nuclear export, is currently being developed as a preclinical anti-cancer agent." (PMID 25476752, 2014).
cancer (continued). "Recently, the protein exportin 1 (XPO1, also called Chromosome Region Maintenance protein 1 [CRM1]) has been validated as a target for therapeutic intervention in cancer." (PMID 25022346, 2014). "Recent studies using both human and murine cancer cell lines have demonstrated that XPO1 is a relevant target for therapeutic intervention." (PMID 25022346, 2014). "The targeting of XPO1 by nuclear export inhibitors (NEI) induces apoptosis in cancer cell lines and slows tumor growth in xenograft mouse models." (PMID 25476752, 2014). "Clinical studies in DLBCL have given insights into how XPO1 may affect cancer and the anti-cancer immune response." (PMID 40291981, 2025). "Proteins involved in histone modification, DNA repair, and transcriptional repression rely on nuclear-cytoplasmic shuttling via XPO1, suggesting that its inhibition may alter chromatin accessibility and gene expression programs in cancer cells." (PMID 41440011, 2025). "In addition to the cancer cell intrinsic pro-apoptotic activity, increasing evidence suggests that XPO1 inhibition has immunomodulatory properties." (PMID 40291981, 2025). "XPO1 is overexpressed in multiple different cancer types, including colon cancer." (PMID 40601866, 2025). "As such, the inhibitory NKG2A:HLA-E axis may be modulated by XPO1 inhibition via two mechanisms within the TME: downregulating HLA-E on cancer cells and dampening IL-10 production." (PMID 40291981, 2025). "Furthermore, in multiple cancer types, XPO1 inhibition increases nuclear FoxO3a intracellular localization both in vivo and in vitro." (PMID 40601866, 2025). "Furthermore, XPO1's expression correlates with tumor mutational burden (TMB) and MSI, suggesting its involvement in genomic instability that drives cancer progression." (PMID 39882192, 2025). "For this reason, Exportin 1 is regarded as a possible therapeutic target in cancer therapy." (PMID 40001478, 2025). "Thus, the combination of high levels of both XPO1 and NK cell infiltration exerts a cancer-specific protective effect on long-term survival in cancer." (PMID 39178254, 2024). "This article concludes with the clinical implications of nuclear export inhibitors, particularly XPO1, as a therapeutic target in various cancers, with selective inhibitors of nuclear export compounds demonstrating efficacy in both hematological and solid malignancies." (PMID 39459201, 2024). "XPO1 overexpression is a common feature among many human cancer types." (PMID 39513105, 2024). "We have used this feature to analyze the charge distribution of the four amino acid residues C-terminal to putative NESs (nuclear export signals) predicted in proteins differentially exported in cells expressing a cancer-related mutant form of the nuclear export receptor CRM1/XPO1." (PMID 39135888, 2024). "Using RNAi screening of the commonly activated molecular programs, we found a signature of three proteins - RUVBL1, HSPA9, and XPO1, which could be efficiently targeted by novel drug combinations in the studied cancer types." (PMID 39217152, 2024). "XPO1 is responsible for the nuclear export of proteins containing a nuclear export signal, which also includes some tumour-suppressor genes, making this gene a target for cancer therapy." (PMID 38641660, 2024). "Overexpression of XPO1 has been observed in a variety of cancers including LPS." (PMID 39606156, 2024). "XPO1 inhibitors Selinexor have been demonstrated to exert antitumor activity in a broad range of cancer types including MM28, while the mechanism of XPO1 overexpression remains unknown." (PMID 39513105, 2024). "Identifying synergistic approaches, whether by disrupting the NPC structure to block transport or inhibiting XPO1 to prevent the export of tumor-suppressor proteins, is a critical aspect of ongoing cancer therapy research." (PMID 39459201, 2024). "This is consistent with our analysis finding the upregulated expression of XPO1 in pan‐cancer." (PMID 39177040, 2024).
cancer (continued). "Therefore, screening specific inhibitors against XPO1 can be used as broad‐spectrum anti‐cancer drugs." (PMID 39177040, 2024). "We examined the role of nuclear to cytoplasmic transport genes including XPO1 in human cancer." (PMID 38302473, 2024). "In addition, we showed that selinexor, a selective inhibitor of XPO1 that has been used as a pan-cancer agent in preclinical and phase I clinical trials, effectively inhibits the growth of AML cells harboring the NPM1-fusions, as it does in NPM1c AML." (PMID 39443736, 2024). "Exportin‐1 (XPO1) mediates the nuclear export of cancer‐related cargoes." (PMID 38783482, 2024). "This could lead to the identification of easily measurable biomarkers of response for XPO1 inhibition that would allow more precise decision‐making for patients receiving this type of cancer therapy." (PMID 36722323, 2023). "Overexpression or dysfunction of XPO1 has been reported in different cancers." (PMID 36979474, 2023). "Oral small molecules such as XPO1 inhibitors offer the potential to improve T-cell fitness and augment cancer cell immune susceptibility without negatively impacting T-cell health." (PMID 37954586, 2023). "There is therefore a strong rationale for inhibiting XPO1 in cancer." (PMID 37601856, 2023). "Inhibition of the XPO-1 (exportin 1) nuclear export pathway with nuclear export inhibitors can overcome this restriction by trapping restriction factors in the nucleus and allow significantly enhanced viral replication and killing of cancer cells." (PMID 37377603, 2023). "Furthermore, knockdown of XPO-1 significantly enhanced MYXV replication in restrictive human cancer cells and reduced the formation of antiviral granules associated with RNA helicase DHX9." (PMID 37377603, 2023). "Studies have shown that XPO1 played a cancer-promoting role in various cancers 26-28." (PMID 37082728, 2023). "We used TCGA and GTEx pan‐cancer database to evaluate XPO1 mRNA expression in various tumors." (PMID 36200270, 2023). "It would be worthwhile testing whether M1-21 acts as an inhibitor for CDK1 or XPO1 in future studies, as it might inhibit cancers synergistically by targeting multiple oncoproteins at the same time." (PMID 37344857, 2023). "Using TCGA and GTEx pan‐cancer database, we evaluated XPO1 mRNA expression in various tumors." (PMID 36200270, 2023). "We reasoned that the co-expression of cancer-related genes and XPO1 may imply a possible cooperation to promote cancer cell progression and possibly drug resistance." (PMID 37046649, 2023). "These markers could lead to the identification of response upon XPO1 inhibition for more accurate decision‐making in the personalized treatment of cancer patients undergoing treatment with selinexor." (PMID 36722323, 2023). "Upregulation of XPO1 expression is evident in multiple solid and haematological malignancies and selective inhibitors of nuclear export (SINEs) induce cancer cell apoptosis via restoration of tumour suppressor protein function and inhibition of oncoprotein translation." (PMID 36560403, 2022). "Overall, these bioinformatics analysis results indicated that XPO1 inhibitor KPT-330 could induce important changes related to cancer pathways in GBC cells." (PMID 36180918, 2022). "XPO1 inhibitors, with their inhibitory effects on various tumorigenic pathways, synergize with multiple antineoplastic agents used in hematological neoplasms and other cancers." (PMID 35091658, 2022). "The suppression of XPO1 is a potential target for many cancer therapeutic interventions." (PMID 34975332, 2022). "Also, multiple reports implicate XPO1 to be a general vulnerability across several types of cancers." (PMID 35573474, 2022). "Selinexor, a specific inhibitor of XPO1 nuclear export protein is approved for cancer treatment." (PMID 36506529, 2022).
cancer (continued). "Moreover, XPO1 was identified to be a dependency in at least 90% of cancer cell lines in a genome wide CRISPR/Cas9 screen performed on 808 cell lines (Cancer Dependency Map Project), putting it into the category of “common essential gene”." (PMID 35573474, 2022). "Therefore, XPO1 is considered an effective target for the treatment of cancer, inflammation, and autoimmune diseases, through the regulation of nuclear–cytoplasmic localization of important proteins." (PMID 35721113, 2022). "Indeed, XPO1 overexpression correlates with poor prognosis of cancer patients and drug resistance of their disease." (PMID 34802051, 2022). "When XPO1 inhibitors are combined with PIs, levels of TSPs and other proteins are greatly increased, and they are restricted to the nuclear compartment leading to greatly enhanced anti-cancer activity." (PMID 34802051, 2022). "Because XPO1 is overexpressed in a number of cancers, it appears that XPO1 mediated nuclear export may be harnessed by various cancers as a general mechanism of oncogenesis." (PMID 35573474, 2022). "XPO1 is reported to be overexpressed in certain types of cancer." (PMID 38938904, 2022). "Notably, XPO1 levels are elevated in various cancers leading to nuclear depletion of tumor-suppressing proteins." (PMID 35047088, 2021). "Thus, their synthesis, antiproliferative activity against a panel of cancer cell lines, XPO1 inhibition and docking studies at the NES-binding cleft of XPO1 are here described." (PMID 34832913, 2021). "As such, restoration of nuclear‐cytoplasmic protein homeostasis via XPO1 inhibition may represent a viable therapeutic strategy for human and canine cancers." (PMID 33438820, 2021). "Although significant research has focused on integration of selinexor into the treatment regimens of adult cancers, it is increasingly recognized that XPO1-directed therapy may be effective as part of management of childhood cancers." (PMID 34944778, 2021). "Finally, we will outline potentially promising future therapeutic strategies for, as well as potential challenges to, integrating XPO1 inhibition to improve outcomes for children with cancer." (PMID 34944778, 2021). "In adult cancers, pharmacologic targeting of XPO1 decreases C-MYC levels." (PMID 34944778, 2021). "Preliminary evidence of the in vitro activity of verdinexor has been documented in several canine cancer cell lines and verdinexor exhibits biologic activity in canine lymphoma patients; however, XPO1 expression and therapeutic targeting of XPO1 in canine OS has not been evaluated." (PMID 33438820, 2021). "Overexpression, deregulation or dysfunction of XPO1 have been reported in various types of cancer." (PMID 33007990, 2020). "In addition, emerging studies have revealed that exportin-1(XPO1) is involved in chemoresistance in many cancers, and XPO1 inhibitor, Selinexor, has been gradually accepted as an effective alternative to overcome chemoresistance." (PMID 32661323, 2020). "XPO1 overexpression correlates with poor prognosis in various cancers, whereas either targeting XPO1 alone by the selective inhibitors of nuclear export (SINE) or in combination with other targeted therapies or chemotherapies shows broad anticancer effect and acceptable tolerance." (PMID 31113936, 2019).
cancer (continued). "Therefore, we clarify the reason of apoptosis resistance of cancer cells to XPO1 inhibition and develop a potential strategy for treating solid tumors." (PMID 31113936, 2019). "The in vitro experiments showed a great impact of KPT-330, as XPO1 inhibitor, to inhibit cancer growth in dose and time dependent manner and significantly diminished the colony formation (P<0.001) of HT29 cells- associated with the expression of Ki67 (P<0.001)." (PMID 31870117, 2019). "In order to evaluate whether the miR-30 family could control cancer cell growth through the regulation of XPO1 expression, we transfected miR-30a and miR-30b mimics into MiaPaCa-2 and Panc-1 cells." (PMID 31382411, 2019). "It is well known that the high expression of XPO1 promotes cancer cell growth." (PMID 31382411, 2019). "Hence, dual treatment with both Topo IIα inhibitor and XPO1 inhibitor is likely to improve the efficacy of cancer therapy." (PMID 31088931, 2019). "The mechanism of XPO1 upregulation in cancer cells is still not well understood." (PMID 31088931, 2019). "Interestingly, recent reports have been published on the functional role of XPO1 and the effect of cancer by inhibition of XPO1‐mediated transport." (PMID 31018022, 2019). "The high expression of XPO1 in cancer cells could be, in part, due to the methylation of the miR-30 gene, leading to the low expression level of the miR-30 family which directly regulates the XPO1 expression." (PMID 31382411, 2019). "Recently, XPO1 inhibition was shown to downregulate MYC expression in several cancer cell lines." (PMID 31752970, 2019). "Moreover, the increased expression of XPO1 has been correlated with the poor prognosis of patients with tumors and an increased proliferative activity of cancer cells." (PMID 31382411, 2019). "XPO1 has been known to promote tumor growth in various cancers." (PMID 31382411, 2019). "In cancer, the disruption of XPO1 activity may be involved in the increasing of survival and proliferative rate activity of tumor cells." (PMID 31870117, 2019). "Furthermore, higher levels of XPO1 expression are correlated with reduced overall survival in many cancers, including MM." (PMID 29876006, 2018). "In addition, XPO1 inhibition in mammalian cells slows cancer progression by preventing the XPO-1-mediated export of tumor-suppressing proteins." (PMID 29768192, 2018). "Additionally, TCGA (The Cancer Genome Atlas) data, indicated that there was an increase in XPO1 gene copy number in cancer tissue." (PMID 30349650, 2018). "Thus, leptomycin B shows anti-cancer effects in SI-NET cells and suggests exportin-1 as a therapeutic target to restore the correct localization of tumor suppressors and other regulators of cancer growth." (PMID 30045709, 2018). "Numerous studies use SINE to probe the anti-cancer potential of inhibiting XPO1 function." (PMID 28467801, 2017). "In addition, several tumor suppressor proteins (TSP) and growth regulatory proteins (GRP) are mislocalized in cancer cells by overexpression and activity of XPO-1." (PMID 29340049, 2017). "Selinexor, a Selective Inhibitor of Nuclear Export (SINE) compound, exerts its anti-cancer effect by binding to and inhibiting exportin 1 (XPO1), which is the main nuclear export protein for hundreds of cargoes including tumor suppressor proteins (TSPs) and growth regulatory proteins." (PMID 29299164, 2017). "Therefore, the next step of implementing XPO1 occupancy in a clinical trial is to perform the assay with purified cancer cells from hematological patient bone marrow." (PMID 26654943, 2016). "In an effort to understand selinexor-XPO1 interaction and to establish whether cancer cell response is a function of drug-target engagement, we developed a quantitative XPO1 occupancy assay." (PMID 26654943, 2016).